CSNK2A2 (casein kinase 2 alpha 2)
Description:
Catalytic subunit of a constitutively active serine/threonine-protein kinase complex that phosphorylates a large number of substrates containing acidic residues C-terminal to the phosphorylated serine or threonine. Regulates numerous cellular processes, such as cell cycle progression, apoptosis and transcription, as well as viral infection. May act as a regulatory node which integrates and coordinates numerous signals leading to an appropriate cellular response. Phosphorylates a number of DNA repair proteins in response to DNA damage, such as MDC1, RAD9A, RAD51 and HTATSF1, promoting their recruitment to DNA damage sites. Can also negatively regulate apoptosis. Phosphorylates the caspases CASP9 and CASP2 and the apoptotic regulator NOL3. Phosphorylation protects CASP9 from cleavage and activation by CASP8, and inhibits the dimerization of CASP2 and activation of CASP8. Regulates transcription by direct phosphorylation of RNA polymerases I, II, III and IV. Also phosphorylates and regulates numerous transcription factors including NF-kappa-B, STAT1, CREB1, IRF1, IRF2, ATF1, SRF, MAX, JUN, FOS, MYC and MYB. Phosphorylates Hsp90 and its co-chaperones FKBP4 and CDC37, which is essential for chaperone function. Regulates Wnt signaling by phosphorylating CTNNB1 and the transcription factor LEF1. Acts as an ectokinase that phosphorylates several extracellular proteins. During viral infection, phosphorylates various proteins involved in the viral life cycles of EBV, HSV, HBV, HCV, HIV, CMV and HPV. May phosphorylate histone H2A on 'Ser-1'.
Synonyms: CK2A2; CSNK2A1; CK2alpha'
Tractability: Small molecule: a structure with a bound ligand is known; a high-quality ligand is known; it has a high-quality binding pocket; it belongs to a druggable protein family. PROTAC: it is named in the literature on targeted protein degradation; ubiquitination databases record sites on it; its protein half-life has been measured; a small molecule that binds it is known.
Target class: Enzyme; Other protein kinase group; Protein Kinase; Other protein kinase CK2 family; Kinase
Chemical probes: GW869516X (high quality), PD155978 (high quality), SGC-CK2-1 (high quality), SGC-CK2-2 (high quality)
Gene: Protein-coding gene on chromosome 16 (58,157,907 to 58,198,191, reverse strand). Ensembl gene ENSG00000070770.
Subcellular location: Nucleus; Cytoplasm
Pathways (Reactome):
Gene expression (Transcription): RUNX1 interacts with co-factors whose precise effect on RUNX1 targets is not known
Signal Transduction: Regulation of PTEN stability and activity; WNT mediated activation of DVL
Autophagy: Receptor Mediated Mitophagy
Cell Cycle: Condensation of Prometaphase Chromosomes
Cell-Cell communication: Regulation of CDH1 posttranslational processing and trafficking to plasma membrane
Cellular responses to stimuli: KEAP1-NFE2L2 pathway
Circadian clock: Phosphorylation and nuclear translocation of the CRY:PER:kinase complex
Developmental Biology: Signal transduction by L1
Disease: Maturation of hRSV A proteins
Immune System: SPOP-mediated proteasomal degradation of PD-L1(CD274)
Metabolism: Synthesis of PC
Metabolism of proteins: Cooperation of PDCL (PhLP1) and TRiC/CCT in G-protein beta folding
Gene Ontology:
Molecular function: protein binding; protein serine kinase activity; protein serine/threonine kinase activity; ATP binding; protein kinase activity
Biological process: double-strand break repair; negative regulation of proteasomal ubiquitin-dependent protein catabolic process; positive regulation of establishment of protein localization to mitochondrion; regulation of chromosome separation; regulation of mitophagy; heterochromatin formation; negative regulation of apoptotic signaling pathway; positive regulation of DNA-templated transcription; cerebral cortex development; liver regeneration; regulation of protein catabolic process; spermatogenesis
Cellular component: nucleus; PcG protein complex; chromatin; cytoplasm; cytosol; nucleoplasm; PRC1 complex; acrosomal vesicle
Genetic constraint (gnomAD): Loss-of-function variants: 6 observed, 27.9 expected, observed/expected ratio (o/e) 0.22, 90% interval 0.12 to 0.42. The upper end of that interval is the gene's LOEUF score, 0.42, which puts it in group 1 of 6, group 1 being the genes least tolerant of losing a copy. Missense variants: 185 observed, 339.66 expected, observed/expected ratio (o/e) 0.54, 90% interval 0.48 to 0.62. Synonymous variants: 114 observed, 121.09 expected, observed/expected ratio (o/e) 0.94, 90% interval 0.81 to 1.1.
Homologues: Orthologues: chimpanzee CSNK2A2 (100% identical), macaque CSNK2A2 (100% identical), pig CSNK2A2 (99% identical), mouse Csnk2a2 (99% identical), guinea pig CSNK2A2 (99% identical), dog CSNK2A2 (93% identical), rat Csnk2a2 (92% identical), zebrafish csnk2a2b (86% identical), tropical clawed frog csnk2a2 (85% identical), zebrafish csnk2a2a (83% identical), rabbit CSNK2A2 (77% identical), Caenorhabditis elegans kin-3 (76% identical), and 1 more. Paralogues in human: CSNK2A1 (83% identical), CSNK2A3 (83% identical).
Diseases named in the same sentence as CSNK2A2 in open-access papers:
CSNK2A2 is named in the same sentence as 42 diseases in open-access papers, as found by Europe PMC text mining. Sharing a sentence is not in itself a finding about the gene and the disease. The quoted sentences say what the papers report.
breast carcinoma (4 papers, 2014 to 2024). "Thus, determining the pathophysiological role of CSNK2A2 loss in breast cancer is important, as it may provide further information on the distinct roles of the two CK2 catalytic subunits." (PMID 25153725, 2014). "RNA expression levels of CDC2L1, CDC2L2, CCNL1, CCNL2, CSNK2A1, CSNK2A2, and CSNK2B genes in breast cancer subtypes were analyzed." (PMID 25837326, 2015).
ovarian carcinoma (4 papers, 2018 to 2024). A malignant neoplasm originating from the surface ovarian epithelium. "Consistent with the involvement of microtubules and CSNK2 in late stages of cancer, overexpression of CSNK2A2 is associated with poor prognosis in ovarian cancer, while its inhibition reduces tumor growth and metastatic colonization." (PMID 38753413, 2024). "CSNK2A2 is found to be correlated with ovarian cancer patient survival." (PMID 29439675, 2018). "Furthermore, the down-regulation of CSNK2A2 will decrease the proliferation of ovarian cancer cells." (PMID 29439675, 2018).
Globozoospermia (3 papers, 2019 to 2023). Any structural anomaly of the acrosome resulting in a round sperm head. "Casein kinase IIα' polypeptide (Csnk2a2) was the first introduced protein whose gene was associated with globozoospermia." (PMID 30291685, 2019). "It expressed in late stages of spermatogenesis, and male mice in which Csnk2a2 has been disrupted are infertile, with oligospermia and globozoospermia (‘round-headed’ spermatozoa)." (PMID 36891514, 2023). "Knockout mice approach for different purposewhich later exhibited globozoospermia manifestation.The target genes were as: Csnk2a2, GOPC, Gba2,PICK1, iii." (PMID 30291685, 2019).
Parkinson disease (3 papers, 2020 to 2023). A progressive degenerative disorder of the central nervous system characterized by loss of dopamine producing neurons in the substantia nigra and the presence of Lewy bodies in the substantia nigra and locus coeruleus. "Furthermore, it is crucial to note that high abundant proteins were linked to a variety of diseases like Pathways of neurodegeneration-multiple diseases (CSNK2A2, HSPA5, etc.; p-value = 5.34E-08) and Parkinson’s disease (LOC101906363, etc.; p-value = 3.94E-07)." (PMID 36891514, 2023).
Alzheimer disease (2 papers, 2018 to 2025). A progressive, neurodegenerative disease characterized by loss of function and death of nerve cells in several areas of the brain leading to loss of cognitive function such as memory and language. "PANTHER pathways analysis of differentially expressed proteins revealed overrepresentation of Wnt signaling pathway (CDH1, CSNK2A2, GNA11, CTBP2, CDH17, SMARCE1, p-value 0.02), followed by Alzheimer disease-presenilin pathway (MMP8, MMP9, MLLT4, CDH1, P-value 0.04)." (PMID 29515771, 2018).
gastric cancer (2 papers, 2013 to 2024). A primary or metastatic malignant neoplasm involving the stomach. "That, and perhaps targeting casein kinase 2-alpha 2 (CK2A2) expression, could explain why the restoration of miRNA-1228 in gastric cancer tissue suppresses EMT." (PMID 39201656, 2024).
hepatocellular carcinoma (2 papers, 2023 to 2025). A malignant tumor that arises from hepatocytes. "CSNK2A2 has been shown to be a significant biomarker of prognosis in hepatocellular carcinoma and might also be linked with the pathogenesis of abdominal aortic aneurysm." (PMID 37231440, 2023). "LGALS3BP is suspected to be a tumor suppressor due to its under-expression in prostate cancer, while CSNK2A2 over-expression promotes tumor progression, particularly in hepatocellular carcinoma." (PMID 39941055, 2025).
Obesity (2 papers, 2010 to 2021). Accumulation of substantial excess body fat. "CSNK2A2 expression might be regarded as an indicator of susceptibility to heart disease, but this gene might be novel target for obesity." (PMID 34248836, 2021).
acute myeloid leukemia (1 paper, 2023). Acute myeloid leukemia (AML) is a group of neoplasms arising from precursor cells committed to the myeloid cell-line differentiation. "Interestingly, PIP4K2C expression has been associated with outcomes in Acute Myeloid Leukemia (AML), while CSNK2A2 has been associated significantly with prognoses of 14 different cancer types (Strum, Gyenis & Litchfield, 2022)." (PMID 38025707, 2023).
breast tumors (1 paper, 2014). "Approximately 30% and 20% of breast tumors have gains on CSNK2A1 (encoding CK2α) and CSNK2B (CK2β), respectively, while fewer gains are seen on CSNK2A2 (CK2α’)." (PMID 25153725, 2014).
chronic lymphocytic leukemia (1 paper, 2018). "Inhibition of CSNK2A2 by CX-4945 also exhibits anti-tumor activity in chronic lymphocytic leukemia." (PMID 30040819, 2018).
colon cancer (1 paper, 2020). "Specifically, CSNK2A2 protects colon cancer cells from TRAIL-induced apoptosis." (PMID 32244548, 2020).
dementia (1 paper, 2025). Loss of intellectual abilities interfering with an individual's social and occupational functions. "Analyzing this dataset we found a specific increase in the expression of CSNK2a2, encoding for CK2α’, but not in CSNK2a1, encoding for CK2α, in patients with dementia compared to non-dementia controls in the PCx." (PMID 40799762, 2025).
endometriosis (1 paper, 2024). The growth of functional endometrial tissue in anatomic sites outside the uterine body. "Moreover, cyto-hub gene analysis revealed that CSNK2A1, CSNK2A2, TOP1, PRKACA, RBM39 (plasma), ALB, ACTB, GAPDH, FN1, APOA1 (serum), S100-A9, CXCL1, IL1RN, CSTA, S100-A8 (menstrual blood) and THBS1, ALB, CD44, ANXA2, and LUM (urine) were the top 5 proteins expressed in women with endometriosis." (PMID 39061077, 2024).
Huntington disease (1 paper, 2011). Huntington disease (HD) is a rare neurodegenerative disorder of the central nervous system characterized by unwanted choreatic movements, behavioral and psychiatric disturbances and dementia. "The gene MAPK8 was reported to be involved in Huntington's disease and the genes WIF and CSNK2A2 are known to participate in the Wntpathway which was reported to be linked to HD." (PMID 22162763, 2011).
lymphoid tumors (1 paper, 2015). "GEP of the available study confirmed the trend of the immunohistochemical results, with high CSNK2A1, CSNK2A2 and CSNK2B mRNA levels in all the considered lymphoid tumors." (PMID 25788269, 2015).
myelofibrosis (1 paper, 2022). A partial or complete replacement of the bone marrow stroma by fibrous tissue. "Interestingly, fedratinib, a selective oral JAK2 inhibitor recently approved in the United States for treatment of adult patients with myelofibrosis, which has off-target activity against the VIPs BRD4, TBK1, MARK1 and CSNK2A2, also displayed a similar proviral effect in our disease system." (PMID 36305426, 2022).
pancreatic cancer (1 paper, 2018).
prostate tumor (1 paper, 2025). "CSNK2A2 has been reported as a marker of PCa progression and prognosis, while DECR1 acts as an androgen-repressed survival factor that regulates PUFA oxidation to protect prostate tumor cells from ferroptosis." (PMID 40626556, 2025).
renal carcinoma (1 paper, 2024). A carcinoma arising from the epithelium of the renal parenchyma or the renal pelvis. "The sensitivity of renal cancer cell lines to 1C8 may also be related to CSNK2A2, which is a target in renal cancer." (PMID 38753413, 2024).
schizophrenia (1 paper, 2024). A major psychotic disorder characterized by abnormalities in the perception or expression of reality. "Finally, we identified CSNK2B, TOMM40, MAP1LC3B, MFN1, CSNK2A2, PGAM5 and ATG12 as the diagnostic genes for schizophrenia." (PMID 39355378, 2024).
cancer (11 papers, 2009 to 2025). A tumor composed of atypical neoplastic, often pleomorphic cells that invade other tissues. "Then, risk scores were calculated for every cancer sample calculated by using the following formula: Riskraw = DAD1*2.316+CYCS*1.426+CSNK2A2*1.576+VPS25*0.728+VDAC1*0.976+TMLHE*0.381+CYTH3*0.024+PRKCA*0.260-TP73*0.567+FZD6*0.047+SQSTM1*0.094-MAP2K7*3.070." (PMID 35185897, 2022). "Abnormal expression of CSNK2A2 has been implicated in various diseases, including cancer." (PMID 41442907, 2025). "For example, the understudied “Dark” kinases PIP4K2C and CSNK2A2 appear in the top 25 features of the best-performing model, suggesting possible functional roles in cancer cell viability." (PMID 38025707, 2023). "We also observed that HDAC8 expression was positively correlated with CSNK2A1, CSNK2A2, and CSNK2B in multiple cancer types in public databases." (PMID 40013761, 2025). "BMX, BMPR1B, BTK, and MDC1 belong to the COSMIC_mut gene set, and CSNK2A2 belongs to the COSMIC_other gene set, while ASH2L belongs to the non-cancer gene set." (PMID 19765316, 2009). "In addition, based on the known functional roles in cancer and the reported classification of the kinase family, PRKD1, PRKD3, BCKDK, PDK2, and CSNK2A2 were considered as potential CCA-relative PKs, which were related to the six overlapped PKs." (PMID 36231050, 2022).
tumor (9 papers, 2015 to 2025). "LGALS3BP and CSNK2A2 are associated with the NF-κB pathway, which is crucial in tumor progression." (PMID 39941055, 2025). "Briefly, the tumor (N = 7) and adjacent (N = 6) tissues of OS patients were collected and stained using IHC, showing that CSNK2A2, VDAC2, and MIF were markedly upregulated in OS tissues compared with the control tissues, whereas the expression of ODC1 showed no significant change." (PMID 37231440, 2023). "To figure out the mechanism underlying the tumor-suppressive effect of FTO expression on BCa cells, we detected the expressions of the known differentially m6A methylated genes, including MALAT1, CSNK2A2, ITGA6, and NOTCH1, which were found to correlate with BCa progression in previous studies." (PMID 34499008, 2021). "IHC staining of tumor and adjacent healthy tissues indicated up-regulation of the VDAC2, CSNK2A2, and MIF genes in tumor tissues, although the expression levels of ODC1 did not change, possibly because of the large differences in the positive signal values between the various samples." (PMID 37231440, 2023).
neurodegenerative disease (1 paper, 2025). A disorder of the central nervous system characterized by gradual and progressive loss of neural tissue and neurologic function. "Furthermore, CSNK2A2, validated by ELISA assays, is implicated in neuronal activities and exhibits a strong association with the pathogenesis of neurodegenerative diseases." (PMID 41465406, 2025).
CSNK2A2 also shares sentences with these, for which no sentence is quoted: diabetes (2 papers); prostate carcinoma (2); abdominal aortic aneurysm (1); acute kidney injury (1); autoimmune disorders (1); breast adenocarcinoma (1); colorectal cancer (1); COVID-19 (1); heart disease (1); infection (1); infertile (1); lung carcinoma (1); metastatic tumor (1); mucopolysaccharidosis type 2 (1); oligospermia (1); parasitemia (1); preeclampsia (1); type 2 diabetes mellitus (1).